FCHSD2 (FCH and double SH3 domains 2)
Description:
Adapter protein that plays a role in endocytosis via clathrin-coated pits. Contributes to the internalization of cell surface receptors, such as integrin ITGB1 and transferrin receptor. Promotes endocytosis of EGFR in cancer cells, and thereby contributes to the down-regulation of EGFR signaling. Recruited to clathrin-coated pits during a mid-to-late stage of assembly, where it is required for normal progress from U-shaped intermediate stage pits to terminal, omega-shaped pits. Binds to membranes enriched in phosphatidylinositol 3,4-bisphosphate or phosphatidylinositol 3,4,5-trisphosphate. When bound to membranes, promotes actin polymerization via its interaction with WAS and/or WASL which leads to the activation of the Arp2/3 complex. Does not promote actin polymerization in the absence of membranes.
Synonyms: NWK1; KIAA0769; SH3MD3; NWK
Tractability: Antibody: UniProt places it where antibodies can reach, with high confidence; its Gene Ontology location is reachable by antibodies, with high confidence. PROTAC: ubiquitination databases record sites on it; its protein half-life has been measured.
Gene: Protein-coding gene on chromosome 11 (72,836,742 to 73,142,346, reverse strand). Ensembl gene ENSG00000137478.
Subcellular location: Cytoplasm; Cell junction; Membrane, clathrin-coated pit; Cell membrane; Cell projection, stereocilium
Subcellular location (Human Protein Atlas): Actin filaments; Plasma membrane; Focal adhesion sites; Nuclear speckles
Gene Ontology:
Molecular function: phosphatidylinositol-3,4,5-trisphosphate binding; phosphatidylinositol-3,4-bisphosphate binding; protein binding
Biological process: clathrin-dependent endocytosis; positive regulation of Arp2/3 complex-mediated actin nucleation; neuromuscular synaptic transmission; positive regulation of actin filament polymerization; regulation of actin filament polymerization; membrane organization; positive regulation of cytoskeleton organization; positive regulation of supramolecular fiber organization; regulation of actin filament organization
Cellular component: anchoring junction; clathrin-coated pit; plasma membrane; cytoplasm; neuromuscular junction; recycling endosome; stereocilium shaft; stereocilium
Genetic constraint (gnomAD): Loss-of-function variants: 16 observed, 52.18 expected, observed/expected ratio (o/e) 0.31, 90% interval 0.21 to 0.47. The upper end of that interval is the gene's LOEUF score, 0.47, which puts it in group 2 of 6, group 1 being the genes least tolerant of losing a copy. Missense variants: 407 observed, 528.84 expected, observed/expected ratio (o/e) 0.77, 90% interval 0.71 to 0.83. Synonymous variants: 164 observed, 194.88 expected, observed/expected ratio (o/e) 0.84, 90% interval 0.74 to 0.96.
Homologues: Orthologues: chimpanzee FCHSD2 (100% identical), macaque FCHSD2 (99% identical), rabbit FCHSD2 (98% identical), guinea pig FCHSD2 (97% identical), mouse Fchsd2 (96% identical), pig FCHSD2 (96% identical), rat Fchsd2 (96% identical), dog FCHSD2 (93% identical), tropical clawed frog fchsd2 (84% identical), zebrafish FCHSD2 (55% identical), Drosophila melanogaster nwk (36% identical), Caenorhabditis elegans C26C6.8 (8% identical). Paralogues in human: FCHSD1 (37% identical).
Diseases named in the same sentence as FCHSD2 in open-access papers:
FCHSD2 is named in the same sentence as 15 diseases in open-access papers, as found by Europe PMC text mining. Sharing a sentence is not in itself a finding about the gene and the disease. The quoted sentences say what the papers report.
lung cancer (2 papers, 2020 to 2023). A malignant neoplasm involving the lung. "Although they are correlative, these data are consistent with our in vitro findings that FCHSD2 functions as a negative regulator of Rab7 and controls lung cancer aggressiveness." (PMID 32678845, 2020).
acute myeloid leukemia (1 paper, 2020). Acute myeloid leukemia (AML) is a group of neoplasms arising from precursor cells committed to the myeloid cell-line differentiation. "The complex effects of altered CME capacity on oncogenesis may depend on the tumor cell type as reflected by the fact that high FCHSD2 levels are correlated with increased survival in NSCLC, whereas elevated FCHSD2 may hamper survival in acute myeloid leukemia." (PMID 33024932, 2020).
Crohn disease (1 paper, 2019). A gastrointestinal disorder characterized by chronic inflammation involving all layers of the intestinal wall, noncaseating granulomas affecting the intestinal wall and regional lymph nodes, and transmural fibrosis. "Genome-wide association studies identified FCHSD2 as a novel susceptibility gene for Crohn’s disease in Korean and Japanese populations." (PMID 31712601, 2019).
lung adenocarcinoma (1 paper, 2020). A carcinoma that arises from the lung and is characterized by the presence of malignant glandular epithelial cells. "As expected from our in vitro findings, FCHSD2 expression is gradually decreased in higher grades of lung adenocarcinoma tumors." (PMID 32678845, 2020). "Correspondingly, we also observed a progressive decrease in FCHSD2 protein levels detected by immunohistochemistry in higher grade of lung adenocarcinomas." (PMID 32678845, 2020). "To investigate the correlation between FCHSD2 activity and lung tumor progression, we directly measured the protein expression level of FCHSD2 in tumor tissues from lung adenocarcinoma patients." (PMID 32678845, 2020). "Notably, the correlation between the expression of FCHSD2 or Rab7 with survival rates was more prominent in lung adenocarcinoma patients." (PMID 32678845, 2020).
non-small cell lung carcinoma (1 paper, 2020). A group of at least three distinct histological types of lung cancer, including non-small cell squamous cell carcinoma, adenocarcinoma, and large cell carcinoma. "In fact, while a number of cancer cells show ERK- and FCHSD2-dependent upregulation of endocytosis, in non-small-cell lung cancer (NSCLC) loss of function of FCHSD2 has been suggested to promote cell proliferation and migration." (PMID 33024932, 2020).
tumor (4 papers, 2015 to 2023). "Correspondingly, FCHSD2 loss correlates to higher tumor grades of NSCLC." (PMID 32678845, 2020). "Whether human FCHSD2 also functions in endosomal trafficking of RTKs to regulate their oncogenic signaling from endosomes and whether this affects human tumor progression have not been studied." (PMID 32678845, 2020).
cancer (2 papers, 2020). A tumor composed of atypical neoplastic, often pleomorphic cells that invade other tissues. "We previously showed that FCH/F-BAR and Double SH3 Domain-Containing Protein (FCHSD2) has a cancer-cell specific function in regulating CME in non-small-cell lung cancer (NSCLC) cells." (PMID 32678845, 2020). "We previously showed that FCHSD2 has a cancer-cell–specific function in positively regulating CME downstream of ERK1/2 activity." (PMID 32678845, 2020). "As in cancer cells, siRNA-mediated KD of FCHSD2 significantly reduced TfnR recycling in ARPE-19 cells, although the effects were somewhat smaller." (PMID 32678845, 2020). "This study defines an endocytic trafficking pathway regulated by FCHSD2 and Rab7 that controls receptor tyrosine kinase expression and oncogenic signal transduction, opening the possibility of novel therapeutic strategies for cancer." (PMID 32678845, 2020). "The effects of FCHSD2 on CME require its activation by ERK phosphorylation and appear to be specific to cancer cells." (PMID 32678845, 2020). "We previously reported that activation of FCHSD2 by ERK1/2 phosphorylation increases the rate of TfnR and EGFR internalization by CME and suppresses signaling from cell surface EGFRs, specifically in cancer cells." (PMID 32678845, 2020). "Whether and to what extent FCHSD2 expression and/or activation plays a role in regulating membrane trafficking and ERK1/2 signaling in other NSCLC cell lines or other cancer types are worth investigating in future experiments." (PMID 32678845, 2020).
adenocarcinoma (1 paper, 2020). A common cancer characterized by the presence of malignant glandular cells. "Further studies will be needed to compare FCHSD2 expression in normal versus adenocarcinoma cancerous lung tissues." (PMID 32678845, 2020).
FCHSD2 also shares sentences with these, for which no sentence is quoted: atherosclerosis (2 papers); autoimmune disease (1); diabetes (1); Hypertension (1); metabolic syndrome (1); retinal degeneration (1); systemic lupus erythematosus (1).